FPGS (folylpolyglutamate synthase)
Description:
Catalyzes conversion of folates to polyglutamate derivatives allowing concentration of folate compounds in the cell and the intracellular retention of these cofactors, which are important substrates for most of the folate-dependent enzymes that are involved in one-carbon transfer reactions involved in purine, pyrimidine and amino acid synthesis. Unsubstituted reduced folates are the preferred substrates. Metabolizes methotrexate (MTX) to polyglutamates.
Tractability: Small molecule: a high-quality ligand is known; it belongs to a druggable protein family. PROTAC: ubiquitination databases record sites on it; a small molecule that binds it is known.
Target class: Enzyme; Ligase
Gene: Protein-coding gene on chromosome 9 (127,794,597 to 127,814,494, forward strand). Ensembl gene ENSG00000136877.
Subcellular location: Mitochondrion inner membrane (Isoform 1); Mitochondrion matrix; Cytoplasm (Isoform 2)
Pathways (Reactome):
Metabolism: Metabolism of folate and pterines
Gene Ontology:
Molecular function: tetrahydrofolylpolyglutamate synthase activity; acid-amino acid ligase activity; ATP binding
Biological process: tetrahydrofolylpolyglutamate biosynthetic process; folic acid metabolic process; nucleobase-containing compound metabolic process; folic acid-containing compound biosynthetic process
Cellular component: cytoplasm; mitochondrial inner membrane; mitochondrial matrix; mitochondrion; cytosol
Genetic constraint (gnomAD): Loss-of-function variants: 53 observed, 56.76 expected, observed/expected ratio (o/e) 0.93, 90% interval 0.75 to 1.17. The upper end of that interval is the gene's LOEUF score, 1.17, which puts it in group 5 of 6, group 1 being the genes least tolerant of losing a copy. Missense variants: 667 observed, 717.05 expected, observed/expected ratio (o/e) 0.93, 90% interval 0.87 to 0.99. Synonymous variants: 330 observed, 313.94 expected, observed/expected ratio (o/e) 1.05, 90% interval 0.96 to 1.15.
Homologues: Orthologues: chimpanzee FPGS (99% identical), macaque FPGS (91% identical), pig FPGS (87% identical), dog FPGS (86% identical), guinea pig FPGS (82% identical), mouse Fpgs (81% identical), rat Fpgs (81% identical), rabbit FPGS (68% identical), tropical clawed frog fpgs (62% identical), zebrafish fpgs (57% identical), Caenorhabditis elegans F25B5.6 (34% identical), Drosophila melanogaster Fpgs1 (32% identical), and 1 more.
Diseases named in the same sentence as FPGS in open-access papers:
FPGS is named in the same sentence as 30 diseases in open-access papers, as found by Europe PMC text mining. Sharing a sentence is not in itself a finding about the gene and the disease. The quoted sentences say what the papers report.
acute lymphoblastic leukemia (9 papers, 2014 to 2025). Leukemia with an acute onset, characterized by the presence of lymphoblasts in the bone marrow and the peripheral blood. "A study examined whether abnormal AS of the FPGS gene promoted MTX resistance in MTX-resistant acute lymphoblastic leukaemia (ALL) cell lines compared to their parental counterparts." (PMID 40282556, 2025). "This study aimed to evaluated whether the A22G polymorphism in the FPGS gene is associated with an increased risk of acute lymphoblastic leukemia (ALL) and whether it plays a role in increasing the survival of patients with ALL." (PMID 25013492, 2014). "Another example is that the intergenic single-nucleotide polymorphism of DHFR and FPGS could affect the levels of MTX in the serum, which results in inadequate treatment intensity and disease relapse after HD-MTX treatment in acute lymphoblastic leukemia patients." (PMID 35223507, 2022). "FPGS rs1544105C > T polymorphism may modify FPGS expression and affect treatment outcome in B-cell precursor acute lymphoblastic leukemia (BCP-ALL) patients." (PMID 25765001, 2015). "Consequently, treatment with HDACIs would alter the FPGS promoter acetylation status and increase FPGS gene transcription and intracellular accumulation of long-chain MTX-PGs based on in vitro tests of acute lymphoid leukemia cell lines." (PMID 32793886, 2020). "Alternative splicing of FPGS has been shown to affect drug metabolism and resistance in acute lymphoblastic leukemia (ALL) by modulating folate homeostasis, and since the folate has been shown to improve MASLD, similar splicing alterations of FPGS may also influence fatty liver development." (PMID 41516281, 2025).
leukemia (4 papers, 2014 to 2025). A malignant (clonal) hematologic disorder, involving hematopoietic stem cells and characterized by the presence of primitive or atypical myeloid or lymphoid cells in the bone marrow and the blood. "However, substitution of the G569 residue located near the A562 residue, with a cysteine, resulted in the loss of 87% of FPGS activity in antifolate resistant human leukemia cells, strongly indicating that this region is highly important for FPGS activity." (PMID 25229333, 2014). "Thus far, three naturally occurring mutations have been shown to underlie loss of FPGS function in leukemia cells: C388F decreased the affinity of FPGS for glutamate by 23-fold." (PMID 25229333, 2014). "Hence, we were now able to detect multiple single nucleotide substitutions in the FPGS gene in various antifolate resistant leukemia sublines." (PMID 25229333, 2014). "A previous study reported that a murine leukemia cell line acquired PEM resistance by decreasing the expression of SLC19A1 and FPGS without an increase in the TYMS expression." (PMID 29682186, 2018).
rheumatoid arthritis (3 papers, 2016 to 2022). A chronic, systemic autoimmune disorder characterized by inflammation in the synovial membranes and articular surfaces. "A recent study has described that altered folylpolyglutamate synthetase (FPGS) pre‐mRNA splicing is associated with unresponsiveness to antifolate agent methotrexate in rheumatoid arthritis." (PMID 36221913, 2022). "In a recent study conducted in patients with rheumatoid arthritis, it was shown that rs1544105 ‘CT’ genotype carriers of the FPGS gene, but not ‘TT’ carriers, had an increased risk of MTX-induced toxicity." (PMID 32481505, 2020).
gastric cancer (2 papers, 2020 to 2023). A primary or metastatic malignant neoplasm involving the stomach. "When the eight characteristic genes (ENTPD3, PDZD4, CNN1, GTPBP4, FPGS, UTP25, CENPW, and FAM111A) are all fitted into one variable, the AUC of the ROC curve is 0.996, indicating a good diagnostic efficiency for gastric cancer." (PMID 37007099, 2023). "First, the expression levels of GGH and FPGS mRNA in gastric cancer tissue and adjacent normal mucosa were compared." (PMID 31754833, 2020). "GGH and FPGS mRNA expression was measured by qPCR to evaluate their clinicopathological significance in gastric cancer patients after curative resection." (PMID 31754833, 2020). "We have established the early diagnosis model of eight characteristic genes (ENTPD3, PDZD4, CNN1, GTPBP4, FPGS, UTP25, CENPW, and FAM111A) for gastric cancer." (PMID 37007099, 2023). "Next, the relationship between the expression levels of GGH and FPGS mRNA and the clinicopathological features in patients with stage II/III gastric cancer were examined." (PMID 31754833, 2020). "In this study, we measured the levels of GGH and FPGS mRNA expression in cancer tissues and adjacent normal mucosa in patients with stage II/III gastric cancer." (PMID 31754833, 2020).
thymic carcinoma (2 papers, 2019 to 2020). Thymic carcinoma (TC) is a type of thymic epithelial neoplasm characterized by a high malignant potential. "In addition, increased expression of tumor-associated genes, such as FPGS (folylpolyglutamate synthase)/GGH (gamma-glutamyl hydrolase) and VEGF (vascular endothelial growth factor), were found to be related to the degree of malignancy in thymic carcinoma and B3 thymoma." (PMID 32993581, 2020).
Burkitt lymphoma (1 paper, 2020). A rare form of malignant mature B-cell non-Hodgkin lymphoma. "We evaluated cell viability after MTX treatment and leucovorin rescue and compared the expression of folylpolyglutamate synthetase (FPGS), γ-glutamyl hydrolase (GGH), and DHFR in 2 human PCNSL-derived cell lines (HKBML and TK) and a human Burkitt lymphoma cell line (TL-1)." (PMID 32793886, 2020).
colorectal cancer (1 paper, 2013). A primary or metastatic malignant neoplasm that affects the colon or rectum. "Given that rs1544105 polymorphism might influence FPGS mRNA levels, and altered FPGS expression was found associated with outcome of colorectal cancer patients, we analyzed the correlation between FPGS rs1544105 genotypes and outcomes in 164 patients." (PMID 24168269, 2013).
malaria (1 paper, 2010). Malaria is a serious and sometimes fatal disease caused by a parasite that commonly infects a certain type of mosquito which feeds on humans. "Unusually for a eukaryote, the malaria parasite Plasmodium falciparum expresses dihydrofolate synthase (DHFS) and folylpolyglutamate synthase (FPGS) as a single bifunctional protein." (PMID 20350571, 2010).
melanoma (1 paper, 2016). A malignant, usually aggressive tumor composed of atypical, neoplastic melanocytes. "SK-MEL-1 melanoma cells proliferation was altered after miR-4286 inhibitor application, which matched the changes in the levels of folylpolyglutamate synthase (FPGS), an enzyme crucial for survival of dividing cells." (PMID 28005927, 2016). "Indeed, miR-4286 inhibition resulted in degradation of folylpolyglutamate synthase, RNA polymerase I-specific transcription initiation factor, apelin, G-protein-coupled receptor 55, and high-mobility group A1 protein mRNA in BRO melanoma cells, as measured by real-time PCR." (PMID 28005927, 2016).
myeloid leukemia (1 paper, 2019). A clonal proliferation of myeloid cells and their precursors in the bone marrow, peripheral blood, and spleen. "Moreover, we investigated the expression of FPGS because it is the determinant enzyme for MTX-PG synthesis and accumulation, mostly in B-ALL compared with T-ALL and myeloid leukemia, in which its activity is twofold lower." (PMID 31779260, 2019).
myeloma (1 paper, 2020). "The relative mRNA expression levels of four folate pathway genes (RFC, GGH, FPGS and DHFR) were examined in eight myeloma cell lines, including four resistant lines (ARP-1, CAG, RPMI 8228, U266) and four sensitive lines (ARH-77, KMS-11, MM.1s, PCNY-1B)." (PMID 32405334, 2020).
osteosarcoma (1 paper, 2022). A usually aggressive malignant bone-forming mesenchymal neoplasm, predominantly affecting adolescents and young adults. "Additionally, SKA1 inhibits FPGS transcription by physically interacting with RPB3 to cause osteosarcoma cells to become resistant to MTX." (PMID 36462498, 2022).
prostate carcinoma (1 paper, 2023). A carcinoma that arises from epithelial cells of the prostate gland. "We validated the expression levels of 5 prognostic genes in the TCGA-PRAD and found that both ATCAY and GLUL were lower expressed in the tumor tissues than normal prostate tissues, while the ASNS, CAD and FPGS were overexpressed in the prostate cancer group." (PMID 36983244, 2023).
psoriasis (1 paper, 2009). An autoimmune condition characterized by red, well-delineated plaques with silvery scales that are usually on the extensor surfaces and scalp. "We conclude that genetic variation across the genes FPGS, GGH, MTHFR and ATIC is not predictive of either efficacy or toxicity of methotrexate in patients with psoriasis." (PMID 19016697, 2009).
steatosis (1 paper, 2025). Increased lipid within the cytoplasm of cells. "In hepatocytes, methotrexate (MTX) is converted to MTX-polyglutamate (MTX-PGs) by folylpolyglutamate synthase (FPGS) leading to apoptosis, fibrosis, oxidative stress, inflammation, and steatosis." (PMID 39979397, 2025).
tumor (14 papers, 2011 to 2025). "In conclusion, we identified a highly potent polyglutamylation-independent antifolate that selectively suppresses growth of methotrexate- or 5-FU-resistant, FPGS-deficient tumor cells." (PMID 37591722, 2023). "We hypothesized that C1 treatment may prevent outgrowth of FPGS-deficient clones in a heterogeneous tumor and thereby overcome methotrexate resistance." (PMID 37591722, 2023). "After LV injection, a significantly higher gene expression level of GGH, MTHFD1L, SLC19A1/RFC-1, and FPGS was seen in tumour tissue compared to mucosa." (PMID 30269276, 2018). "The results of the study showed that tumour tissue of untreated patients had higher expression of FPGS, GGH, MTHFD1L, and SLC19A1/RFC-1 compared with mucosa, whereas expression of ABCC3/MRP3 and SLC46A1/PCFT was higher in mucosa compared with tumour." (PMID 30269276, 2018). "Pralatrexate is a dihydrofolate reductase (DHFR) inhibitor with high affinity for reduced folate carrier 1 (RFC-1) and folylpolyglutamate synthetase (FPGS), resulting in extensive internalization and accumulation in tumour cells." (PMID 21179031, 2011). "Pralatrexate is an antifolate with high affinity for the reduced folate carrier 1 (RFC-1) protein and folylpolyglutamate synthetase (FPGS), resulting in extensive internalization and accumulation within tumour cells." (PMID 21179031, 2011). "In this respect, we herein uncovered that the 3′UTR of FPGS, the GQ motifs in particular, induce cell invasion in response to pulse folic acid (FA) repletion, suggesting a role in tumor progression, migration, and metastasis under low folate conditions in the tumor microenvironment." (PMID 36721160, 2023). "After LV injection, the expression of FPGS, GGH, MTHFD1L, and SLC19A1/RFC-1 was significantly higher in tumour tissue compared to the mucosa." (PMID 30269276, 2018). "Expression of FOLR1, FPGS, MLH1 and TYMS (each p<0.0001) differed significantly between all four tumor types." (PMID 27064343, 2016). "Actually, we previously reported that the gene expression levels of folylpolyglutamate synthase (FPGS) and gamma-glutamyl hydrolase (GGH) in tumors could predict the levels of reduced folate after LV administration in tumor tissue." (PMID 28417167, 2017). "Hence, for these 7 genes (TS, FPGS, GGH, DHFR, ERCC-1, TOPO-1, and EGFR), evaluation of their expression by biopsy would reflect the mRNA expression in the whole tumor and would therefore permit their use in the clinic." (PMID 23577026, 2013). "However, since FPGS is likely an essential gene in many eukaryotic cells, tumor cells must strike a balance, reducing MTX activity without compromising their own survival." (PMID 41269429, 2025). "In the present study, both FPGS and GGH were expressed at higher levels in tumors compared to mucosa, indicating an increased intracellular folate turnover in tumors, a finding further supported by the high expression of the proliferation marker TYMS in tumor tissue." (PMID 39998667, 2025).
cancer (12 papers, 2011 to 2023). A tumor composed of atypical neoplastic, often pleomorphic cells that invade other tissues. "Mechanistic characterization of a novel, lipophilic antifolate that suppresses growth of FPGS-deficient cells that are linked to methotrexate resistance and relapse in cancer patients." (PMID 37591722, 2023). "Our novel findings reveal that the GQ motifs in the 3′UTR of FPGS regulate its transcript and protein localization at cell protrusions in response to a folate cue, thereby inducing cancer cell invasion." (PMID 36721160, 2023). "Collectively, the GQ motifs within the 3′UTR of FPGS regulate its transcript and protein localization at cell protrusions in response to a folate cue, inducing cancer cell invasive phenotype." (PMID 36721160, 2023). "Human FPGS, the ortholog of Met7, has been shown to play a central role in determining the success of anti-folate treatment against cancer cells." (PMID 24728996, 2014). "In fact, the crucial role of FPGS has been demonstrated via diminished or loss of FPGS activity, which was found to result in the lack of MTX responsiveness and acquired MTX resistance in both RA and cancer." (PMID 37298590, 2023). "A positive correlation between pralatrexate sensitivity and mRNA expression of FPGS, a major enzyme responsible for polyglutamation of antifolates, was found in the 15 cancer cell lines, suggesting an important role of polyglutamation in cellular response to pralatrexate." (PMID 21179031, 2011). "Thus, GGH and FPGS strongly influence DNA synthesis in cancer cells." (PMID 31754833, 2020). "This suggests a role for FPGS, not only in intracellular folate retention and homeostasis, but also in folate sensing and chemotaxis, highlighting FPGS 3′UTR GQ motifs as an attractive druggable target for inhibition of cancer migration and invasion." (PMID 36721160, 2023). "Several previous studies have compared the relative expression levels of GGH and FPGS mRNA between various types of cancer tissue and adjacent normal tissue." (PMID 31754833, 2020).
FPGS also shares sentences with these, for which no sentence is quoted: breast carcinoma (2 papers); thymoma (2); acute myeloid leukemia (1); B-cell precursor acute lymphoblastic leukemia (1); bladder cancers (1); colon cancer (1); hairy cell leukemia (1); hepatoma (1); infection (1); lymphoma (1); mesothelioma (1); nasopharyngeal carcinoma (1); non-Hodgkin lymphoma (1).